FAM30A (family with sequence similarity 30 member A)
Synonyms: C14orf110; KIAA0125; HSPC053
Gene: Long non-coding RNA gene on chromosome 14 (105,879,976 to 105,932,642, forward strand). Ensembl gene ENSG00000226777.
Diseases named in the same sentence as FAM30A in open-access papers:
FAM30A is named in the same sentence as 26 diseases in open-access papers, as found by Europe PMC text mining. Sharing a sentence is not in itself a finding about the gene and the disease. The quoted sentences say what the papers report.
gastric cancer (5 papers, 2021 to 2025). A primary or metastatic malignant neoplasm involving the stomach. "The role of FAM30A in cancer is only reported in laryngeal squamous cell carcinoma, gastric cancer and chronic lymphocytic leukaemia, and in‐depth studies are lacking." (PMID 39972942, 2025). "In contrast, FAM30A expression was increased in gastric cancer (GC) cell lines, and patients with GC who had high FAM30A expression had poor survival outcomes." (PMID 36159965, 2022). "In addition, FAM30A is reported to be a biomarker in many types of tumors, like gastric cancer, lung adenocarcinoma, laryngeal squamous cell carcinoma, and AML." (PMID 34904791, 2022). "In this study, we used bioinformatic methods to identify FAM30A and TIMD4 as possible biomarkers for predicting gastric cancer metastasis." (PMID 34476011, 2021).
gallbladder cancer (4 papers, 2017 to 2024). "Gallbladder cancer development might be related to H19 and FAM30A." (PMID 35571069, 2022).
laryngeal squamous cell carcinoma (4 papers, 2022 to 2025). A squamous cell carcinoma that arises from the larynx. "FAM30A has previously been shown to inhibit the proliferation, invasion, and migration of laryngeal squamous cell carcinoma cells in vitro." (PMID 36159965, 2022).
leukemia (4 papers, 2020 to 2026). A malignant (clonal) hematologic disorder, involving hematopoietic stem cells and characterized by the presence of primitive or atypical myeloid or lymphoid cells in the bone marrow and the blood. "Similarly, the FAM30A gene has been recently shown to be associated with leukemia stemness and high-risk pediatric AML57." (PMID 37798266, 2023).
periodontitis (4 papers, 2020 to 2026). An acute or chronic inflammatory process that affects the tissues that surround and support the teeth. "BACKGROUND: This study investigated the expression patterns of lncRNA FAM30A in periodontitis, evaluated its diagnostic value, and elucidated the underlying molecular mechanisms." (PMID 41820893, 2026). "CONCLUSION: The present study first demonstrates that FAM30A is a promising diagnostic biomarker, which is strongly linked to periodontitis staging (Stage I/II vs. Stage III/IV) and thus offers a new approach for clinical diagnosis." (PMID 41820893, 2026). "FAM30A was found to be differentially upregulated in periodontitis and to be positively associated with the proportion of plasma cells." (PMID 36159965, 2022). "RESULTS: The FAM30A levels rose significantly in GCF of periodontitis patients and in P.g-LPS-stimulated hPDLCs, while miR-28-5p expression dropped markedly." (PMID 41820893, 2026). "For example, the expression level of FAM30A in periodontitis was positively related to the proportion of plasma cells in inflammatory tissue." (PMID 34306024, 2021). "Network analysis results revealed that FAM30A was involved in the immune response in periodontitis, with B cell activation and immune-related gene alteration." (PMID 32411181, 2020). "Additionally, silencing FAM30A may alleviate the progression of periodontitis by regulating the miR-28-5p/KAT6A axis, reducing inflammation, and promoting bone formation." (PMID 41820893, 2026). "The PCR results, consistent with the microarray chip data, demonstrated that all the differentially expressed lncRNAs (FAM30A, GUSBP11, and LINC00525) were upregulated in periodontitis compared with those in controls." (PMID 32411181, 2020). "Besides, the level of lncRNAs (FAM30A, GUSBP11, and LINC00525) expression were positively correlated with the fraction of plasma cells in periodontitis." (PMID 32411181, 2020).
colon cancer (3 papers, 2020 to 2025). "Overexpressing FAM30A also weakened the cell spheroidisation ability of colon cancer cells." (PMID 39972942, 2025).
rheumatoid arthritis (2 papers, 2022 to 2023). A chronic, systemic autoimmune disorder characterized by inflammation in the synovial membranes and articular surfaces. "Meanwhile, FAM30A has been found to play an important role in rheumatoid arthritis." (PMID 36159965, 2022). "The third lncRNA, FAM30A, has previously been detected to interact with hub genes in a WGCNA analysis of a rheumatoid arthritis study, with our study revealing a similar central role of FAM30A in LN for the first time." (PMID 37475860, 2023).
tumor (15 papers, 2020 to 2025). "A prominent association was observed in FAM30A with tumor–node–metastasis stage (P = .022), carcinoembryonic antigen (P = .027), and differentiation (P = .043) of CRC patients." (PMID 39128096, 2024). "Based on the results in this research, understanding FAM30A specific role in CRC can help inhibit the tumour progress and enhance the clinical applicability." (PMID 39972942, 2025). "We will further investigate the underlying mechanisms by which FAM30A expression influences the infiltration of immune cells in CRC and how they contribute to anti‐tumour immune responses." (PMID 39972942, 2025). "Our research uncovered the vital role of FAM30A in the prognostic forecasting of CRC and exposed the potential molecular mechanism of FAM30A, which suggests the crucial role of lncRNAs in the progression of tumor-related research." (PMID 39128096, 2024). "FAM30A also served as a tumor suppressor inhibiting cell growth and metastasis via negatively modulating miR-21-3p." (PMID 39128096, 2024). "The EOI residual blast cells depicted overexpression of multiple genes associated with tumor growth and poor outcome including HOPX, SELENOP/SEPP1, and FAM30A/C1orf11053–55." (PMID 37798266, 2023). "The residual blast cells depicted overexpression of multiple genes associated with tumor growth (SELENOP), metabolism, and stemness (HOPX, FAM30A)." (PMID 37798266, 2023). "Our results showed that FAM30A or TIMD4 expression was upregulated in tumor tissues compared with paired corresponding normal tissues (P < 0.001)." (PMID 34476011, 2021). "Furthermore, the dual luciferase reporter assays were employed to assess the interactions between FAM30A and miR-21-3p and to evaluate the role of miR-21-3p in regulating the tumor suppressor effects of FAM30A." (PMID 39128096, 2024). "In conclusion, downregulated FAM30A in CRC predicted poor prognosis and severe development of patients and served as a tumor suppressor via negatively modulating miR-21-3p." (PMID 39128096, 2024). "Among them, FAM30A, HCP5, LINC00963, TMEM147-AS1, and TTTY15 indicated a worse prognosis, but LINC00342, MEG3, HCG18, and N4BP2L2-IT2 demonstrated a better tumor prognosis." (PMID 35615374, 2022). "Furthermore, eight target genes (COL4A3, FAM30A, FCRL5, MDM4, SYNE2, TNFRSF13C, TPTEP2, VAMP1) were systematically positively correlated with ESR2 expression patterns in tumor types with low ESR2 expression as a prognostic factor concerning OS or DFS." (PMID 39201394, 2024). "Notably, our findings highlight seven genes (FAM30A, MDM4, POU2AF1, SYNE2, TNFRSF13C, TPTEP2, VAMP1) presenting positive correlations with ESR2 expression patterns in all tumor types with high ESR2 expression as a positive prognostic factor with regard to OS or DFS." (PMID 39201394, 2024).
cancer (9 papers, 2014 to 2025). A tumor composed of atypical neoplastic, often pleomorphic cells that invade other tissues. "Other significant genes, including RIPOR2, FAM30A, DLX4 and LAT, are associated with inflammatory/immune processes and various cancer etiologies." (PMID 39020437, 2024). "We hope that the role of FAM30A in cancer and the immune microenvironment will be investigated further in the future." (PMID 36159965, 2022). "Previous research has suggested that FAM30A is involved in various cancer." (PMID 39128096, 2024). "Interestingly, CD109 and KIAA0125 (FAM30A) were previously identified by other groups to have prognostic relevance in cancer." (PMID 30050054, 2018). "Then, we identified five truly prognostic lncRNAs (AC107021.2, AC027117.1, FAM30A, FAM83A-AS1, and MED4-AS1) and constructed a ceRNA network, and four hub genes of downstream genes were identified and analyzed using immune, pan-cancer, and survival analyses." (PMID 36159965, 2022). "Although FAM30A is involved in the regulation of immune functions, FAM30A has not been studied in cancers." (PMID 34476011, 2021).
adenocarcinoma (1 paper, 2025). A common cancer characterized by the presence of malignant glandular cells. "Five hundred and thirty‐three common genes co‐expressed with FAM30A were identified from colon (COAD) and rectal (READ) adenocarcinomas in TCGA by using GEPIA." (PMID 39972942, 2025).
FAM30A also shares sentences with these, for which no sentence is quoted: acute myeloid leukemia (4 papers); colorectal cancer (3); lung adenocarcinoma (3); breast carcinoma (2); ameloblastoma (1); bladder cancer (1); chronic lymphocytic leukaemia (1); infarction (1); infection (1); influenza (1); leukocytosis (1); lung carcinoma (1); Mendelian diseases (1); pancreatic ductal adenocarcinoma (1); psychiatric disorder (1); Stroke (1).